TWIST1 (twist family bHLH transcription factor 1)
Diseases named in the same sentence as TWIST1 in open-access papers (continued):
Sharing a sentence is not in itself a finding about the gene and the disease.
tumor (continued). "Steroid receptor coactivator 1 (Src-1) and Twist1 are aberrantly upregulated in a variety of tumors and play an important role in tumor progression." (PMID 30973923, 2019). "We selected the tumor tissue samples to validate the expression relationship among the TWIST1-ceRNET components and obtained consistent results." (PMID 31645542, 2019). "Others report the expression of EMT inducers such as ZEB1 and TWIST1 in surrounding fibroblasts, hence promoting the tumor budding phenotype." (PMID 31316988, 2019). "TWIST1 Overexpression of TWIST1 has been observed in many cancer types and it plays a role in tumor initiation and EMT." (PMID 31752264, 2019). "In fact, previous findings have shown strong correlations between TWIST1 positivity in fibroblasts and high-grade tumor budding areas." (PMID 31316988, 2019). "We have found that Src-1 and Twist1 were aberrantly upregulated in human NPC tissues, and associated with advanced tumor stage, distant metastasis and unfavorable prognosis." (PMID 30973923, 2019). "The significant heterogeneity of PRMT1, ZEB1, and TWIST1 immunostaining was observed among analyzed tumor types (p < 0.001)." (PMID 31655611, 2019). "It has been presented that disseminated tumor cells (DTCs) that enter dormancy and form micrometastasis highly express Twist1 or Snail1, suggesting that EMT contributes to the initial colonization and formation of dormancy." (PMID 31861892, 2019). "This study demonstrated the dependence of Twist1 on TP to regulate tumor metabolic reprogramming and further enriched knowledge on the effects of Twist1 on tumor VM formation and metastasis." (PMID 30674871, 2019). "When TP was knocked down after overexpressing Twist1, the tumor volume and lung metastasis were impaired almost to the control level." (PMID 30674871, 2019). "Twist1 and N-cadherin were highly expressed in metastatic tumor cells, and E-cadherin expression was markedly decreased in the metastatic tumors." (PMID 31934531, 2019). "The TWIST1 expression in stromal fibroblasts was assessed in Korean ESCC patients which was positively correlated with increased depth of tumor invasion, lymph node involvement, stage, and overall survival." (PMID 31470870, 2019). "In summary, our study revealed that the expression of Src-1 and Twist1 was aberrantly upregulated in NPC tissues and was associated with advanced tumor stage, distant metastasis and unfavorable prognosis." (PMID 30973923, 2019). "Comparing to non-tumor samples, significantly lower expression levels of miR-15a-3p, and significnatly lower expression levels of Twist1 mRNA were observed in SCLC tissues (p < 0.05)." (PMID 31842825, 2019). "High Twist1 expression is closely correlated with tumor stage (P = 0.016), recurrence (P = 0.042) and distant metastasis (P = 0.001)." (PMID 30973923, 2019). "TWIST1 over-expression was confirmed as having an essential role in tumor initiation, stemness, angiogenesis, invasion, metastasis, and chemo-resistance in a variety of carcinomas." (PMID 29716631, 2018). "Expression of EMT-inducing transcription factors such as Snail1, Snail2, and Twist1 often correlates with enhanced tumor microvessel vasculature and expression of angiogenic factors." (PMID 29416649, 2018). "The PLC-PRF-5 and HepG2/M xenograft models were used to examine the in vivo effects of PAR1 and Twist1 during tumor growth." (PMID 30081924, 2018). "Nuclear TWIST1 was expressed in 60% (84/140) of tumor cells, of these 51% (72/140) overexpressed it, according to the median value ≥4." (PMID 29716631, 2018). "Here, several tumor EMT markers (Twist1, Snail, MMP1, and MMP9) were evaluated, but metformin did not inhibit EMT in MCF7/ADR." (PMID 29416762, 2018). "Overexpression of PAR1 in the PLC-PRF-5 model significantly increased tumor growth and lung metastasis, whereas knockdown of Twist1 in HepG2/M or PLC-PRF-5 cells overexpressing PAR1 inhibited the promotional effects on tumor progression by PAR1." (PMID 30081924, 2018).
tumor (continued). "In summary, we concluded that ETV6-knockdown leads to derepression of TWIST1 which contributes to tumor progression." (PMID 29455655, 2018). "Expression in CAFs of another transcription protein, Twist1, also correlates with tumor growth, invasion depth and lymph node metastasis." (PMID 30128085, 2018). "In the present study, we investigated promoter methylation in six genes associated with tumour invasivity (ADAM23, uPA, CXCL12, TWIST1, SNAI1 and SNAI2)." (PMID 30189837, 2018). "In our study, we showed that, by sponging miR-200c, lncATB facilitated the expression of Twist1, resulting in promoted tumour progression." (PMID 30518916, 2018). "Stimuli from proinflammatory cytokine IL-6 expressed by tumor cells, is sufficient to induce the expression of Twist1 in normal fibroblasts and transdifferentiate them into CAFs through the activation of STAT3 pathway." (PMID 30175384, 2018). "Our results provide a molecular mechanism by which ETV6 suppresses tumor progression through transcriptional regulation of TWIST1 and disruption of EGFR-RAS signaling." (PMID 29455655, 2018). "It has been also reported that TRIM29 acts as a tumor suppressor through inhibiting Twist-related protein 1 (TWIST1) and suppress epithelial mesenchymal transition (EMT)." (PMID 29552313, 2018). "TWIST1 and C3 colocalized at the invasive tumor edges, and in the neural crest and limb buds of mouse embryos." (PMID 30061895, 2018). "In conclusion, we showed that Sox6 plays a tumour suppressor role in PC, inhibiting EMT and tumour metastasis by modulating Twist1 expression through the recruitment of HDAC1 to the promoter of the Twist1 gene." (PMID 29369542, 2018). "Taken together, our data suggest that HMGA2 directly targets Twist1 and promotes the expression of Twist1 and VE-cadherin, resulting in the formation of VM and enhanced tumour invasion and metastasis." (PMID 28533522, 2017). "The results of in vivo studies suggest that Bcl-2/Twist1 depletion can, to a great extent, inhibit tumor growth and metastasis." (PMID 28032603, 2017). "The direct link of EMT‐TF to tumor metastasis was established upon the discovery of another EMT‐TF, TWIST1 in tumor metastasis." (PMID 28085222, 2017). "In CRC, TWIST1 expression was found to be restricted to tumor cells and correlated with lymph node metastasis and poor prognosis." (PMID 28030836, 2017). "Our results, showed that the expression of HIF-1α correlated with TWIST1 expression in tumor site of the Group 1 patients." (PMID 29152120, 2017). "Many studies have shown that Twist1 is also involved in other facets of tumor invasion and metastasis, such as the formation of invadopodia, intravascular migration, extravasation, and vasculogenic mimicry (VM) formation." (PMID 28099910, 2017). "The most critical pathological function of Twist1 in cancer is facilitating tumor invasion and metastasis by promoting EMT." (PMID 28099910, 2017). "In particular, we analysed the endogenous expression in 5 GCT/PDB tumor tissues of two markers, as FGFR2IIIc and TWIST1, already described as up-regulated in GCT." (PMID 28968976, 2017). "TWIST1-positive stromal cells of human CRC have a fully mesenchymal phenotype and are associated with tumor progression." (PMID 29258163, 2017). "Among the DEGs, Twist1 was found as an important gene closely linked to VHL silencing, which has been reported as an important regulator of tumor neovascularization." (PMID 28710479, 2017). "Results from Western blotting revealed that the protein levels of E-cadherin were upregulated, while the protein levels of vimentin, Snail, Slug, and Twist1 were downregulated in tumor tissues from phenformin-treated mice." (PMID 28947975, 2017). "The role of Twist1 in malignant tumors is associated with initiating tumor EMT and facilitating tumor invasion and metastasis." (PMID 28032603, 2017).
tumor (continued). "In all tumor and paired liver metastasis samples, we found the same proteins behavior, confirming the functional link between nuclear TWIST1 and cytoplasmic β-catenin." (PMID 29152120, 2017). "Twist1 siRNA treatment significantly inhibited the tumor growth and lung metastasis of the HCT-8/V xenograft." (PMID 28881781, 2017). "Twist1 is involved in tumor initiation and progression, which especially contributes to tumor invasion and metastasis." (PMID 28774312, 2017). "We developed a Tca8113 xenograft tumor model by injecting tumor cells in the mouth floor to confirm the consequence of silencing Bcl-2/Twist1 in vivo." (PMID 28032603, 2017). "In response to TWIST1 induction, tumor cells underwent EMT, invaded through the basement membrane, and a large number of circulating tumor cells (CTCs) disseminated into the blood circulation." (PMID 28085222, 2017). "Both clinical and in vitro functional studies indicated that Twist1 enhanced the ability of esophageal fibroblast to promote tumor progression." (PMID 29029429, 2017). "All examined tumours demonstrated Twist1 expression in adherentculture and spheroids, with the nuclear signal being detected in G113 and G114cells but not in G116, where only the cytoplasmic expression pattern wasobserved." (PMID 28522553, 2017). "Twist1 played a decisive role in tumor EMT, similarly, in our research, silencing of Twist1 resulted in a distinguished MET process." (PMID 28032603, 2017). "An animal model derived from the Tca8113 cell line was used to further validate the role of Bcl-2/Twist1 depletion in suppressing tumor EMT and growth." (PMID 28032603, 2017). "In their study, Bcl-2 can bind to Twist1 and formation of the Bcl-2/Twist1 complex facilitates the nuclear transport of Twist1 and increase the tumor cell plasticity, metastasis, and vasculogenic mimicry." (PMID 28032603, 2017). "In low tumor Hp expression group, TWIST1 (r = -0.54, p < 0.01), LAMB1 (r = -0.58, p < 0.001), and THY1 (r = -0.48, p < 0.01) showed negative correlation with Hp." (PMID 28158312, 2017). "On the other hand, shRNA-mediated depletion of Twist1 in esophageal CAFs reduced tumor-promoting ability of CAFs." (PMID 29029429, 2017). "In vitro studies showed that TWIST1 mRNA transcription is regulated by tumor hypoxia in a HIF-1α dependent way." (PMID 29165393, 2017). "The antagonism of these pathways kept the dynamic expression of Twist1, and their fluctuation resulted in distinct consequence of tumor suppression or promotion." (PMID 28394356, 2017). "In the specific tumor environment, Twist1 undergoes relocation into the nucleus to exhibit its transcriptional regulation effect." (PMID 28032603, 2017). "They show that proinflammatory cytokine IL6 that is commonly expressed in tumours was sufficient to induce Twist1 expression in normal cultured fibroblasts and to transdifferentiate them into CAFs through STAT3 phosphorylation." (PMID 28544627, 2017). "Despite structural differences between tumour and control networks, we found a conserved set of associations between miR-200 family members and genes such as VIM, ZEB-1/2 and TWIST-1/2." (PMID 29051564, 2017). "We also assessed the effect of Twist1 on the tumor-promoting ability of esophageal CAFs and normal fibroblasts (NFs) through in vitro and in vivo experiments." (PMID 29029429, 2017). "The Bcl-2/Twist1 complex facilitates Twist1 nuclear transport and leads to transcriptional activation of a wide range of genes that induce tumor cell EET and VM." (PMID 27034014, 2017). "EMT is an essential step in cell metastasis, and many EMT-inducing transcription factors, such as Snail and Twist1, are related to tumor invasion and metastasis." (PMID 28335402, 2017).
tumor (continued). "Knocking down SRC3 reduces the expression of Smad and Twist1 in vitro and suppresses tumor metastasis in vivo." (PMID 28099910, 2017). "Consistent with our results, increased Twist1 and VE-cadherin expression levels were observed in tumours with high HMGA2 expression, while the converse relationship was observed in tumours with shRNA-mediated silencing of HMGA2." (PMID 28533522, 2017). "On the contrary, in both tumor forms we detected a strong TWIST1 expression in the nuclei of mesenchymal lineage cells and a moderate signal in their cytoplasm." (PMID 28968976, 2017). "TWIST1 knockdown decreased invasiveness and sensitized for an ALK inhibitor in cell culture models, thus linking TWIST1 with malignant progression and therapy resistance of this tumor." (PMID 28556516, 2017). "We next evaluated the pro-survival and proliferation phenotype of TWIST1-overexpressing cells in tumour engraftment." (PMID 27876874, 2016). "TWIST1 expression led to increased tumour engraftment in mice, as well as cisplatin resistance in vitro." (PMID 27876874, 2016). "Twist1 is a transcription factor important in embryonic development, and plays an essential role in tumor metastases." (PMID 27074574, 2016). "This review focuses on the role of Twist1-Jagged1/Notch-KLF4 axis on tumor-derived endothelial transdifferentiation, tumorigenesis, metastasis, and cancer stemness." (PMID 26823670, 2016). "Ectopic expression of MACC1 promoted tumor proliferation, significantly upregulated TWIST1 expression in vivo, and induced vascular tube-like formation in vitro." (PMID 27280289, 2016). "Here, we discuss the relationship of the EMT regulator, Twist1, cancer stemness, and tumor angiogenesis." (PMID 26823670, 2016). "Overexpression of miR186 in PC3luc cells strikingly suppressed tumor metastasis in vivo, while re-expression Twist1 in the PC3luc-miR186 cells significantly rescued metastasis formation which was inhibited by overexpression of miR186." (PMID 27121312, 2016). "Prior studies have linked TWIST1 and the related protein TWIST2 to drug resistance in multiple tumour types, including ovarian, but the specific mechanism by which TWIST1 drives resistance in EOC is not well understood." (PMID 27876874, 2016). "More recent work, using conditional knockdown models at various phases of tumor growth, demonstrates that Twist1 is critical for tumor initiation in skin tumorigenesis." (PMID 27023622, 2016). "Lately, activated p38/MAPK has been identified to promote EMT via up-regulating Twist1 or Snail expression in different types of tumor." (PMID 26959880, 2016). "In NPC, Twist1 has also been suggested to contribute to metastasis, malignant progression and drug resistance (Taxol) of tumor." (PMID 27793033, 2016). "We sought to determine the role TWIST1 plays in the acquisition of drug resistance in recurrent tumour cells." (PMID 27876874, 2016). "For example, Twist1 has been shown to contribute to tumor progression either by promoting collective invasion, generating invadopodia, or through induction of an Epithelial-Mesenchymal Transition (EMT)." (PMID 27105506, 2016). "Between one and three weeks, mean tumor volume increased from 100 to 650 mm3 in Twist1-overexpressing LS513 tumors and from 100 to 200 mm3 in control LS513 tumors (P = 0.003)." (PMID 27494849, 2016). "In tumour cells lines, Twist1 and Bmil overexpression would result in the EMT characteristic acquisition and stem cell markers induction, thus to enhance the capacity of tumour invasion and metastasis." (PMID 27027258, 2016). "Tumors grew rapidly after the initial period passed, suggesting that Twist1 affects the late period of tumor development in MSS LS513 tumors." (PMID 27494849, 2016). "HIF-1alpha, a key transcription factor that is induced by hypoxia and is implicated in tumor progression/metastasis, induces EMT through direct activation of Twist1." (PMID 26823670, 2016).
tumor (continued). "It is a new vision that Twist1 can induce transdifferentiation of tumor cells into endothelial cells and promotion of tumor-derived vascular formation." (PMID 26823670, 2016). "For example, Twist1 up‐regulation would significantly enhance the invasiveness and metastasis capacity of tumour cells, as well as promote VM formation and stimulate the secretion of VM‐associated molecules including VE‐cadherin." (PMID 27027258, 2016). "Taken collectively, these data strongly suggest a critical role for TWIST1 in promoting survival, proliferation, and engraftment of tumour cells in the ovaries and peritoneal space." (PMID 27876874, 2016). "Vasculogenic mimicry (VM) is a blood supply modality that is strongly associated with the epithelial-mesenchymal transition (EMT), TWIST1 activation and tumor progression." (PMID 25895023, 2015). "Tumor growth pattern in mice showed that TQ treatment for 3 weeks efficiently inhibited the tumor growth in female BALB/c mice (4T1-ShC-TQ and 4T1-ShT-TQ groups), but TWIST1 knockdown inhibited tumor growth by only some extents." (PMID 26023736, 2015). "Then, we compared the mRNA levels of several TGF-β-related EMT-regulators including SNAI1, SNAI2, HMGA2, FOSL1, SP1, ZEB1, ZEB2 (SIP1), and TWIST1 in primary tumor tissues of MDA-MB-231-xenografted mice." (PMID 26462028, 2015). "Twist1 is involved in development and osteoblast differentiation and has been characterized as an essential player in cancer stem cell generation, tumor invasion and metastasis." (PMID 26361389, 2015). "HIF-1α also increases expression of genes involved in glycolysis, to adapt the tumor to survive under conditions of low oxygen, and genes involved in invasion and metastasis such as Twist1." (PMID 26010887, 2015). "Expression of SNAI1/2, ZEB2 and TWIST1 were observed in the nucleus as well as the cytoplasm of epithelial cells, however, only nuclear staining in normal and tumor epithelial cells was evaluated as these proteins are expected to regulate transcription." (PMID 26214683, 2015). "Recent work also shows that Twist1 is overexpressed in many human cancers and cancer cell lines, thereby driving tumor invasion and metastasis." (PMID 26361389, 2015). "In fact, recent studies have revealed that Twist1 contributes to tumor invasion and dissemination by regulating the expression of TIMP1 or MMPs." (PMID 26538215, 2015). "Overexpression of TWIST-1 in breast cell lines, head and neck squamous cell carcinoma cells, and cervical cancer cells enhanced tumor-initiating and self-renewal capability." (PMID 26023795, 2015). "In this study, we investigated the possible link between TWIST1 and TWIST2 methylation in tumor epithelium and tumor stroma, the relationship with TWIST1 and TWIST2 protein expression and a possible role for these genes in promoting a tumor budding phenotype." (PMID 25528769, 2015). "Thirdly, we performed laser capture microdissection to dissect out tumor epithelium from tumor stroma in regions previously stained for TWIST1 and TWIST2 protein." (PMID 25528769, 2015). "Twist1 was mainly found in the nucleus and cytoplasm of cells and was restricted to tumor glands in IHC staining." (PMID 26360779, 2015). "In contrast, the high-grade budding tumor showed considerable stromal cell staining of TWIST1 and TWIST2 while the low-grade budding cancers had a mostly negative stroma." (PMID 25528769, 2015). "Considering the importance of Twist1 during tumor progression, we strongly believe that our findings will have far-reaching implications in gaining a better understanding of tumor progression in general." (PMID 25847239, 2015). "In contrast, miR-33b knockdown or HMGA2, Twist1 or ZEB1 overexpression significantly attenuated the effect of cordycepin on lifespan of tumor-bearing mice." (PMID 25868853, 2015).